RNU6-732P (RNA, U6 small nuclear 732, pseudogene)
Gene: Small nuclear RNA gene on chromosome 5 (149,057,554 to 149,057,656, reverse strand). Ensembl gene ENSG00000251842.
Homologues: Orthologues: macaque U6 (97% identical), dog U6 (91% identical). Paralogues in human: RNU6-16P (92% identical), RNU6-854P (92% identical), RNU6-1124P (91% identical), RNU6-29P (91% identical), RNU6-403P (91% identical), RNU6-820P (91% identical), RNU6-1152P (90% identical), RNU6-12P (90% identical), RNU6-13P (90% identical), RNU6-25P (90% identical), RNU6-32P (90% identical), RNU6-35P (90% identical), and 1286 more.